RASL12 (RAS like family 12)
Synonyms: RIS
Tractability: Small molecule: a structure with a bound ligand is known. Antibody: its Gene Ontology location is reachable by antibodies, with medium confidence.
Gene: Protein-coding gene on chromosome 15 (65,053,337 to 65,076,690, reverse strand). Ensembl gene ENSG00000103710.
Gene Ontology:
Molecular function: protein binding; GTPase activity; G protein activity; GTP binding
Biological process: small GTPase-mediated signal transduction
Cellular component: plasma membrane
Genetic constraint (gnomAD): Loss-of-function variants: 16 observed, 19.94 expected, observed/expected ratio (o/e) 0.8, 90% interval 0.54 to 1.22. The upper end of that interval is the gene's LOEUF score, 1.22, which puts it in group 5 of 6, group 1 being the genes least tolerant of losing a copy. Missense variants: 306 observed, 331.01 expected, observed/expected ratio (o/e) 0.92, 90% interval 0.84 to 1.02. Synonymous variants: 159 observed, 140.96 expected, observed/expected ratio (o/e) 1.13, 90% interval 0.99 to 1.29.
Homologues: Orthologues: chimpanzee RASL12 (99% identical), macaque RASL12 (98% identical), pig RASL12 (94% identical), rabbit RASL12 (94% identical), rat Rasl12 (94% identical), mouse Rasl12 (94% identical), zebrafish rasl12 (64% identical), tropical clawed frog rasl12 (62% identical). Paralogues in human: REM1 (27% identical), RASL11A (26% identical), REM2 (26% identical), RERG (26% identical), RRAD (25% identical), RIT1 (24% identical), RASL11B (23% identical), RERGL (23% identical), GEM (23% identical), RAP2A (23% identical), DIRAS2 (22% identical), RAP2B (22% identical), and 23 more.
Diseases named in the same sentence as RASL12 in open-access papers:
RASL12 is named in the same sentence as 6 diseases in open-access papers, as found by Europe PMC text mining. Sharing a sentence is not in itself a finding about the gene and the disease. The quoted sentences say what the papers report.
lung adenocarcinoma (1 paper, 2022). A carcinoma that arises from the lung and is characterized by the presence of malignant glandular epithelial cells. "And RASL12 exhibited a diminished expression in lung adenocarcinoma, and its downregulation was positively correlated with better OS." (PMID 36568384, 2022).
tumor (3 papers, 2008 to 2025). "The results suggested that the ENST00000609697–hsa-miR-6791-5p–RASL12 ceRNA network may play a tumor-suppressive role and may contain new therapeutic targets and pathways related to LUAD survival." (PMID 34819106, 2021). "We identified a novel ceRNA network (ENST00000609697–hsa-miR-6791-5p–RASL12) that might play a tumor-suppressive role." (PMID 34819106, 2021). "The ENST00000609697–hsa-miR-6791-5p–RASL12 axis may play a tumor-suppressive role." (PMID 34819106, 2021). "Finally, through analysis of ENST00000609697 target genes, we identified the ENST00000609697–hsa-miR-6791-5p–RASL12 ceRNA network, which may play a tumor-suppressive role in LUAD." (PMID 34819106, 2021). "When combining these findings with our results, we inferred that RASL12 may be a tumor suppressor and that the ENST00000609697–hsa-miR-6791-5p–RASL12 axis may play a tumor-suppressive role in LUAD." (PMID 34819106, 2021). "In addition, knockdown of NDUFA4L2 in HCC cells has been shown to suppress tumor growth and metastasis, which is consistent with our findings of elevated NDUFA4L2, OLFML2B, SEMA5B, and RASL12 expression in HCC tissues and their significant negative correlation with patient survival." (PMID 41208981, 2025). "However, evidence that RASL12 functions as a small GTP-binding protein is lacking; In fact, studies have reported that RASL12 could be homologous to the RAS-like GTPases RERG, RASL11A, RASL11B, RASL10A and RASL10B, which play tumor-suppressive roles in human cancers." (PMID 34819106, 2021).
adenocarcinoma (1 paper, 2015). A common cancer characterized by the presence of malignant glandular cells. "For adenocarcinoma specifically, DM was observed in promoters [hypermethylated RASL12; SPTAN1, mir-26a, hypomethylated NQO1, SIRPB1, NF1A] and gene bodies [hypermethylated AKAP13, ANK family, PRKCE, ROS1; hypomethylated FAM171A1, PARK2, BCAS3, RHOJ] and many others." (PMID 26683690, 2015).
RASL12 also shares sentences with these, for which no sentence is quoted: breast tumors (1 paper); cancer (1); prostate carcinoma (1).